EGFR (epidermal growth factor receptor)
Diseases named in the same sentence as EGFR in open-access papers (continued):
Sharing a sentence is not in itself a finding about the gene and the disease.
tumor (continued). "In the exosome cohort CXCL12 expression was strongly correlated with EGFR status, CD44v6 was associated with tumor stage, TTF-1 expression & chromogranin protein expression and HIF1A & TGFBR2 showed positive correlation with CEA expression & CK20 expression." (PMID 38877052, 2024). "Epidermal growth factor receptor (EGFR) mutations are present in NSCLC and related to tumor response to EGFR tyrosine kinase inhibitors (TKIs), indicating that EGFR constitutes a potential biomarker." (PMID 39514581, 2024). "Despite this generally accepted view, KRAS and EGFR mutations can rarely occur within the same tumor." (PMID 38953007, 2024). "We present two cases of pulmonary papillary adenoma and the corresponding clinicopathological characteristics and report the first instance of EGFR 19 exon mutation in this tumor type." (PMID 38902753, 2024). "To date, many investigations have identified resistance mechanisms using bulk tumor tissues or subcloned resistant cell lines, including EGFR secondary mutation, the activation of alternative signaling pathways, or phenotypic transformation of tumor cells." (PMID 39036343, 2024). "Clinical and pathological phenotypes associated with BRAFV600E-mutated CRC include proximal tumor location, aggressive growth, unfavorable metastasizing patterns, EGFR blockade resistance, and reduced overall survival." (PMID 39199569, 2024). "An association between high expression of EGFR and tumor malignancy, mitotic index, tumor size, dog’s age, and poor prognosis were also found." (PMID 38474142, 2024). "Patient response to EGFR inhibitors is influenced by factors such as tumour sidedness and RAS/BRAF mutational status." (PMID 38414064, 2024). "In clinical practice, the detection of EGFR mutations in tumor tissues primarily relies on surgical or biopsy specimens." (PMID 38982267, 2024). "While numerous models integrating clinical and radiological features have emerged, some have ventured to incorporate serum tumor markers alongside radiological indicators to enhance EGFR mutation prediction." (PMID 39650554, 2024). "The EGFR 19 Del mutation rate was lower in patients with longer tumor long diameters than patients with shorter tumor long diameters (P = 0.009)." (PMID 39364008, 2024). "Mutations in the epidermal growth factor receptor (EGFR) are known to elicit significant tumor responses." (PMID 39702350, 2024). "Regarding the CT features of the lung tumors, the tumor diameter of the EGFR mutation group was significantly smaller than that of EGFR wild-type group (p < 0.001)." (PMID 38783331, 2024). "Nevertheless, the question persists: does a model that synthesizes all three categories of information—serum tumor markers, CT imaging traits, and clinical characteristics—offer superior diagnostic precision for EGFR mutation status?" (PMID 39650554, 2024). "A total of 925 mutant genes encoding tumor-specific antigens were screened by assessing fraction genome alteration and mutation counts in each EGFR-mutant NSCLC patient." (PMID 37388902, 2023). "MET, ERBB2, VEGFR2, PFGFR, and EGFR, among others, represent acknowledged targets of semaphorins that are often associated with tumor progression or poor prognosis." (PMID 38067240, 2023). "We also indicated the tumour stage, the experimental design (P = prospective, R = retrospective, as specified in the Materials and Methods section) and the method of EGFR mutation investigation by liquid biopsy." (PMID 38116291, 2023). "High expression of EGFR is connected to aggressive tumor behavior and high risk metastasis and treatment failure." (PMID 37936777, 2023). "Objective tumor responses were observed in patients with different 20ins variants, prior EGFR TKI treatments and untreated CNS metastases." (PMID 37308490, 2023).
tumor (continued). "Bay846 significantly reduces active, phosphorylated EGFR levels, suppresses tumor cell proliferation, causes tumor cell lysis, and has potent anti-tumor activity, resulting in a high frequency of tumor size regressions." (PMID 36768973, 2023). "The discovery of ligands that bind specifically to cancer cells is essential for NDDS delivery, and peptide binding to liposomes has been used to selectively deliver drugs to kill tumor cells with EGFR mutations." (PMID 37744063, 2023). "Detection of circulating tumor DNA (ctDNA) has recently emerged as an alternative to EGFR mutation testing, but plasma ctDNA mutation detection can be easily affected by tumor burden and has a relatively high false-negative rate." (PMID 38094613, 2023). "These alterations cause conformational changes in the EGFR’s ATP binding site, leading to abnormal activation of downstream signaling pathways responsible for oncogenic addiction in tumor cells." (PMID 37958668, 2023). "For example, Erlotinib [an EGFR inhibitor used in the first line treatment of not small cell metastatic lung cancer (NSCL) showing exon deletions or mutations of EGFR] requires autophagy activation to maximize inhibition of tumor growth." (PMID 36891266, 2023). "EGFR mutation-calling failure was observed in the clinical tumor biopsy NGS record of some patients from which BASELINE (n = 2) and POST2 (n = 1) PDCs were derived." (PMID 36717865, 2023). "In the pathological data collected in this study, in male patients (p = 0.002), patients with EGFR mutations (p < 0.001), Single station lymph node metastasis (p = 0.017) and patients with a tumour diameter ≤ 3 cm (p < 0.001), SKN2 was prone to occur." (PMID 37118722, 2023). "Erlotinib and gefitinib are small molecules that target EGFR tumor mutation and are effective in the treatment of patients with this subgroup of tumors, showing a response rate of approximately 70%." (PMID 36629526, 2023). "Administering EGFR-TKIs to patients scheduled for surgical resection would presumably reduce the differences in overall survival and local tumor control between patients with EGFR mutations and those without." (PMID 36676186, 2023). "The ability to directly assess the attention distribution of MIL models also allows an opportunity to investigate learned patterns regarding tumor biology and the tumor microenvironment (TME) when predicting EGFR mutational status." (PMID 36927889, 2023). "Another previous study in the Lebanese population demonstrated a significant correlation between EGFR mutations and well-differentiated tumor pathology." (PMID 38008767, 2023). "SMARCA4‐dNSCLC was significantly associated with older age, male sex, smoking history, larger invasive tumor size, higher tumor proliferation index (Ki‐67), more adrenal metastases, more lymph node metastases, and few EGFR mutations (p < 0.05)." (PMID 37184108, 2023). "EGFR mutations activate the tyrosine kinase (TK) domain of EGFR exon 19 or 20, resulting in unregulated tumor growth." (PMID 37345192, 2023). "These drugs target these overactive kinases, thereby blocking the signals that contribute to tumor growth, and are particularly effective in patients with EGFR mutations, ALK rearrangements, and ROS1 rearrangements." (PMID 37509204, 2023). "Plasma testing for EGFR mutations offers a minimally invasive alternative to tumour testing and can be used to identify patients with T790M mutations for Osimertinib treatment." (PMID 37894366, 2023). "Some evidence showed that anti-EGFR specific antibody (7A7) can cause significant tumor-specific CTL response, and their clinical efficacy is related to ICD induction." (PMID 37153795, 2023). "There were significant differences in smoking status, tumor subtype, and EGFR mutation status among patients in the three datasets." (PMID 37749461, 2023). "EGFR mutation detection rates in tumor samples and plasma samples were 65.1% (205/315) and 43.8% (138/315)." (PMID 36621813, 2023).
tumor (continued). "A significant association of EGFR expression was observed with age, tumor size, tumor site, histological subtype, histological differentiation, nodal metastasis, ENE, and PNI (p < 0.05)." (PMID 37588336, 2023). "Despite not being previously studied in NSCLC, SBS18 has been associated with tumor metastasis and worse prognosis in breast and prostate cancer and it has been strongly linked with sensitivity to EGFR inhibition to afatinib." (PMID 37653450, 2023). "For example, the accumulation of EGFR in the nucleus can lead to the overexpression of several transcription factors, including c-Myc, which is associated with tumor growth and angiogenesis." (PMID 37580790, 2023). "With the rapid advancement of precision medicine, programmed cell death‐ligand 1 (PD‐L1) expression status in tumor cells has been attracting attention for its relation to the prognostic outcomes associated with EGFR‐TKIs in patients with EGFR‐mutated NSCLC." (PMID 37548381, 2023). "EGFR overexpression was also shown to be associated with melanoma progression and promoted invasiveness and metastasis in this tumor type." (PMID 38201251, 2023). "By liquid biopsy molecular profiling, they demonstrated that these cells also represented the primary tumour, both pathologically and phenotypically, associating the epidermal growth factor receptor (EGFR) pathway with aggressive tumour growth." (PMID 36765175, 2023). "K-Ras mutation does drive quiescent cells to divide via G1 cyclins, and EGFR contributes to the increase in G1 cyclins; moreover, in early cancers, it is essential for tumour progression, however further mutations relieve this requirement." (PMID 36975534, 2023). "On the other hand, the mutation patterns of EGFR were quite diverse between the original tumor and the PDX." (PMID 38001935, 2023). "Right-sided tumours are less responsive to anti-EGFR agents and are associated with worse prognosis compared with left-sided tumours." (PMID 36879000, 2023). "EGFR, an epidermal growth factor family member, is closely associated with cell proliferation, apoptosis and tumour invasion and metastasis in OSA, which is consistent with the findings of this study." (PMID 36611218, 2023). "The efficacy of the Emut Vax was evaluated in both syngeneic and genetic engineered EGFR mutation-driven murine lung tumor models with prophylactic settings, where the vaccinations were given before the onset of the tumor induction." (PMID 36875137, 2023). "The assessment of circulating tumor DNA (ctDNA) is a noninvasive strategy for cancer diagnosis; in particular, plasma ctDNA testing to examine sensitizing EGFR and T790M mutations was approved in 20157." (PMID 38012343, 2023). "Two meta-analyses demonstrated a pooled specificity of 93.5–98% and a sensitivity of 67.4–68% for cfDNA, when plasma samples were tested to determine the EGFR mutational status compared with matched tumor tissues." (PMID 37372399, 2023). "Standard assessment of tumor tissue includes rapid testing for EGFR mutations, ALK fusions and ROS1 fusions." (PMID 37948122, 2023). "We performed the pooled analysis of the CAVE and VELO studies to evaluate the percentage of patients with WT circulating tumor DNA (ctDNA) tumors and the association of mutational status with time from the last anti-EGFR drug administration." (PMID 37046778, 2023).
tumor (continued). "These tumours also had similar detection rates for EGFR mutations and for RET, ROS1, ALK and MET oncogenic isoforms compared with tumours in never-smokers, which suggests that they have a similar aetiology and pathogenesis." (PMID 37046096, 2023). "The response rates to anti-PD-L1/PD-1 treatment according to the presence of EGFR mutation were verified using the TIDE tool or tumor mutation burden (TMB)." (PMID 37033978, 2023). "In the present study, we retrospectively studied the NGS data of treatment-naïve tumor samples from 8485 EGFR-mutated NSCLC patients, of whom 1025 had compound EGFR mutations." (PMID 36829178, 2023). "Generally, these tumors will be classified as GBM because the of release of circulating tumor cells is associated with EGFR gene amplification, indicating that hematogenous GBM spread out is an intrinsic feature of GBM biology." (PMID 36991494, 2023). "As a result, TET1 repression was associated with the hypomethylation of tumor-suppressor genes and EGFR-mediated epigenetic silencing." (PMID 38003512, 2023). "Gatipotuzumab is an anti-tumor-associated epitope of mucin-1 monoclonal antibody and tomuzotuximab is an anti-EGFR antibody." (PMID 36895477, 2023). "In xenograft tumors obtained from the SCCHN cell line FaDu, dacomitinib reduced tumor cell proliferation and EGFR phosphorylation and caused a delay in tumor growth by 13 days in comparison to the control group." (PMID 38201251, 2023). "At the same time, EGFR amplification and Chromosome 7 gain combined 10 loss are associated with increased tumor growth related to AUP1 levels." (PMID 37029364, 2023). "Tumor initiation and development are closely correlated with the epidermal growth factor receptor (EGFR), the most prevalent mutation driver gene in LUAD." (PMID 36756152, 2023). "The results of this prospective study demonstrated that the MassARRAY platform is a system for tumour genotyping to assess the emergence of RAS mutations to evaluate resistance to anti-EGFR treatment." (PMID 37488448, 2023). "EGFR mutation and activation of its mediated signaling pathways contribute to the proliferation of tumor cells." (PMID 37373500, 2023). "Detecting EGFR mutations in tumor tissue samples is sometimes difficult when insufficient tumor material is available and/or poor patient performance status or other clinical limitations do not allow invasive procedures." (PMID 37444638, 2023). "The strong point of the present analysis is that the patients were enrolled consecutively, all of whose tumours were analysed for EGFR mutations unless they were judged insufficient for detecting EGFR mutations." (PMID 37930012, 2023). "This ongoing dynamic resembles an arms race, wherein mutations arise, targeted therapies are developed and applied, and, in response, subsequent secondary mutations of EGFR appear in the tumor clones." (PMID 38201251, 2023). "Based on their clinical utility, we proposed that ctDNA assays for plasma EGFR mutation can be used for cancer screening by comparing the EGFR mutational status of tumor samples at the initial diagnosis and the status of plasma samples at 1-month follow-up." (PMID 37372399, 2023). "In tumor cells, oncogenic mutations in the EGFR, RAS, and Raf genes cause constitutive ERK1/2 activation in the MAPK pathway." (PMID 38005938, 2023). "The EGFR gene encodes the protein located on the cell surface whose activation stimulates the molecular pathways that allow the growth and development of the tumor microenvironment." (PMID 38322283, 2023). "Observational studies have implicated lnc-EGFR in encouraging Treg differentiation and thwarting cytotoxic T lymphocyte-mediated killing, thereby augmenting tumor immune escape." (PMID 37760852, 2023). "The results showed that VAF of some mutations in tumor tissues are significantly higher than those in plasma, e.g. EGFR p.Leu858Arg, KRAS p.Gly12Cys and ALK." (PMID 37004022, 2023).
tumor (continued). "In the pathogenesis of CRC, the EGFR signaling pathway is implicated in the promotion of tumor cell proliferation, migration, inhibition of apoptosis, angiogenesis, and immune evasion by tumor cells." (PMID 37762323, 2023). "Targeted therapy for metastatic lung cancer has been in routine use since pivotal studies showed high response rates and durable responses in individuals with tumours harbouring specific mutations, first related to aberrations in the EGFR and ALK genes." (PMID 36900294, 2023). "In recent years, the resistance of EGFR-TKIs mediated by tumor-associated macrophages (TAMs) has received broad attention." (PMID 37649478, 2023). "By detecting specific genetic mutations, such as IDH1 or EGFR, and monitoring levels of circulating tumor DNA, liquid biopsy can aid in the early detection and monitoring of disease progression." (PMID 37525780, 2023). "ACVR1 and EGFR mutations were mutually exclusive with tumours clustering distinctly by both RNA expression and DNA methylation t-SNE plots, suggesting even further sub-classification within this subgroup." (PMID 36882456, 2023). "Accumulating evidence suggests that oncogenes and tumor suppressors govern EVs secretion, for example, the mutation and/or hyperactivation of EGFR and RAS." (PMID 37495566, 2023). "The combination of savolitinib and osimertinib showed superior anti-tumor activity compared to monotherapy in NSCLC models with EGFR mutations and MET amplification." (PMID 37835402, 2023). "Mutations in EGFR, one of the many tumor drivers, is observed in approximately 15% of non-small cell lung cancer patients." (PMID 37333807, 2023). "Particularly, EGFR mutation decreased INFγ response, which activates the anti-tumor response and is required for response to any type of immunotherapy." (PMID 37165457, 2023). "A patient with multifocal GBM characterized by multiple EGFR mutations had a complete response to compound 4 at only one of the tumor sites." (PMID 36985576, 2023). "Results revealed that arsenic increased the cytosolic expression of LC3 and P62 to a certain extent in tumor cells harboring EGFR WT, EGFR L858R mutation, and T790M mutation." (PMID 37371816, 2023). "Here, our data showed EGFR gene mutation is up to 25.9%, which clue EGFR is heavily involved in tumor genesis of RCC patients." (PMID 37515929, 2023). "In contrast, the effects of gefitinib on tumor cells carrying EGFR L858R and ΔE746-A750 mutations were more obvious (p < 0.01, p < 0.001)." (PMID 37371816, 2023). "As an example, they reported the loss of function mutations of RBM10 that co-occur with mutant EGFR decreased the efficacy of osimertinib in patient-derived EGFR-mutant tumor models." (PMID 37041601, 2023). "EGFRvIII, for instance, is a tumour-specific mutant of EGFR found in a subset of glioblastoma and has been associated with poor prognosis." (PMID 37686020, 2023). "Tumor tissues with higher EGFR VAF were associated with lower cell infiltration such as CD3+ T cells, CD20+ B cells, CD56+ natural killer cells, CD68+ macrophages, CD8+ T cells, and only CD3+ T cells showed a lower spatial distribution heterogeneity." (PMID 37035883, 2023). "EGFR is closely linked to the progression of tumor resistance mechanisms when using anti-cancer medication, accompanied by the marked induction of specific point mutations in EGFR and ALK rearrangements." (PMID 37155147, 2023). "EGFR mutated tumor cells secrete cytokines to recruit various immunosuppressive cells, while activated immune cells (CD8+TRM and CXCL9+TAM) are seriously insufficient." (PMID 37671151, 2023). "Several reports have provided evidence of the efficacy of TKIs such as erlotinib and gefitinib for EGFR mutation-positive cancers and crizotinib for tumours harbouring ALK rearrangements." (PMID 37686122, 2023). "The expression of EGFR increased in tumor-related myeloid cells and was associated with the outcomes of CRC patients." (PMID 37875976, 2023).